SYNGR3 (synaptogyrin 3)
Description:
May play a role in regulated exocytosis. May indirectly regulate the activity of the plasma membrane dopamine transporter SLC6A3 and thereby regulate dopamine transport back from the synaptic cleft into the presynaptic terminal.
Tractability: Antibody: UniProt predicts a signal peptide or a membrane-spanning region. PROTAC: its protein half-life has been measured.
Gene: Protein-coding gene on chromosome 16 (1,989,660 to 1,994,275, forward strand). Ensembl gene ENSG00000127561.
Subcellular location: Cytoplasmic vesicle, secretory vesicle, synaptic vesicle membrane; Synapse
Subcellular location (Human Protein Atlas): Golgi apparatus; Vesicles
Gene Ontology:
Molecular function: protein binding; SH2 domain binding
Biological process: substantia nigra development; positive regulation of transporter activity; regulated exocytosis; regulation of neurotransmitter uptake; regulation of synaptic vesicle priming
Cellular component: membrane; neuromuscular junction; synapse; synaptic vesicle; synaptic vesicle membrane
Genetic constraint (gnomAD): Loss-of-function variants: 9 observed, 12.29 expected, observed/expected ratio (o/e) 0.73, 90% interval 0.44 to 1.28. The synonymous counts are far from expectation, so gnomAD's model fits this gene poorly and the ratio says little. Missense variants: 311 observed, 245.21 expected, observed/expected ratio (o/e) 1.27, 90% interval 1.15 to 1.39. Synonymous variants: 176 observed, 123.01 expected, observed/expected ratio (o/e) 1.43, 90% interval 1.26 to 1.62.
Homologues: Orthologues: macaque SYNGR3 (99% identical), dog SYNGR3 (98% identical), guinea pig SYNGR3 (96% identical), pig SYNGR3 (95% identical), rat Syngr3 (94% identical), mouse Syngr3 (94% identical), tropical clawed frog syngr3 (59% identical), zebrafish syngr3a (59% identical), zebrafish syngr3b (59% identical). Paralogues in human: SYNGR1 (51% identical), SYNGR2 (45% identical), SYNGR4 (34% identical).
Diseases named in the same sentence as SYNGR3 in open-access papers:
SYNGR3 is named in the same sentence as 17 diseases in open-access papers, as found by Europe PMC text mining. Sharing a sentence is not in itself a finding about the gene and the disease. The quoted sentences say what the papers report.
breast cancer (3 papers, 2022 to 2025). A primary or metastatic malignant neoplasm involving the breast. "For example, SYNGR3 was included in a prognostic gene signature as being downregulated in chemotherapy-resistant breast cancer cell lines where addition of a histone deacetylase inhibitor (SAHA) was effective, supporting our finding that high SYNGR3 may indicate better prognosis." (PMID 36148399, 2022).
Alzheimer disease (2 papers, 2020 to 2021). A progressive, neurodegenerative disease characterized by loss of function and death of nerve cells in several areas of the brain leading to loss of cognitive function such as memory and language. "Studies suggest that microtubule-associated protein Tau, implicated in Alzheimer’s disease, interacts with SYNGR3 causing synaptic dysfunction." (PMID 33888815, 2021). "Intriguingly, SYNGR3 was recently reported to mediate pathological Tau protein recruitment to the pre-synapse in Alzheimer’s disease models." (PMID 32686835, 2020).
head and neck cancer (2 papers, 2022). A primary or metastatic malignant neoplasm affecting the head and neck. "Moreover, additional analyses confirm that SYNGR3 expression is high in HPV(+)OPSCC and low in HPV(−) OPSCC, suggesting that SYNGR3 is indeed a diagnostic and prognostic biomarker of head and neck cancers." (PMID 36148399, 2022). "Relative to HPV− head and neck cancers (HNC), HPV+ HNC and cervical cancer showed a significantly increased expression of a number of genes, including SYNGR3." (PMID 35409005, 2022). "To evaluate the utility of SYNGR3 as a novel prognostic immune cell biomarker of HPV(+) HNSC, we used the UCSC Xenabrowser to analyze publicly available RNA-seq data for TCGA head and neck cancer dataset." (PMID 36148399, 2022).
oncocytoma (2 papers, 2010 to 2022). "The reasons underlying the reduced expression of aquaporin 6 and increased expression of synaptogyrin-3 in chRCC, relative to oncocytoma are uncertain." (PMID 20462447, 2010). "Finally, SYNGR3 is differentially expressed in chromophobe renal cell carcinoma compared with nonmalignant oncocytomas and used in a 14-gene probe to distinguish between the two with high degree of accuracy." (PMID 36148399, 2022). "For synaptogyrin-3, both N-18 and C-18 antibodies yielded a similar signal, but the N-18 antibody yielded a crisper result though the maximal signal was distinctly weaker compared to AQP6, for which crisp membranous staining was noted in oncocytoma, but not in chRCC." (PMID 20462447, 2010).
tauopathies (2 papers, 2021 to 2025). "Our data, taken together with the previous animal data, indicate that in primary tauopathies as well as AD, tau-synaptogyrin-3 interactions may be important for synaptic dysfunction and loss." (PMID 40670683, 2025). "Furthermore, Syngr3 may play a role in tauopathies, and the reduction of Syngr3 expression in neurons rescues synaptic plasticity deficits induced by tau." (PMID 34720876, 2021).
age (1 paper, 2023). A temporal measurement of the time period elapsed since an identifiable point in the life cycle of an organism. "Therefore, it is plausible that reduced SYNGR3 expression may impair synaptic function in these age‐related neurodegenerative disorders." (PMID 36624932, 2023).
cervical cancer (1 paper, 2022). A primary or metastatic malignant neoplasm involving the cervix. "The differentially expressed mRNAs in the normal cervical epithelium and primary tumors were detected by an mRNA microarray assay which revealed SYNGR3 as one of the ten most overexpressed potential diagnostic and prognostic biomarkers in cervical cancers compared to the normal cervical epithelium." (PMID 35409005, 2022).
renal carcinoma (1 paper, 2022). A carcinoma arising from the epithelium of the renal parenchyma or the renal pelvis. "For example, gene expression profiling revealed that the differential expression of SYNGR3 is a novel immunohistochemical marker which discriminates two pathologic entities in renal cancers." (PMID 35409005, 2022).
squamous cell carcinoma (1 paper, 2022). A carcinoma arising from squamous epithelial cells. "To further test the association between SYNGR3 expression and HPV status, we next analyzed all available TCGA PanCancer squamous cell carcinoma datasets and confirmed that expression of SYNGR3 is significantly elevated only in HPV(+) tumors." (PMID 36148399, 2022).
synucleinopathies (1 paper, 2022). "Finally, transcripts known to be involved in Tau- and synucleinopathies include IGLON5, CAV1, GFRA2, SYNGR3, and SLC6A3, with the latter being particularly interesting as its genetic variants lead to Parkinsonism-dystonia infantile (PKDYS) syndrome." (PMID 35883433, 2022).
cancer (5 papers, 2021 to 2022). A tumor composed of atypical neoplastic, often pleomorphic cells that invade other tissues. "SYNGR3 has primarily been described as a neuronal synaptic gene; however, some studies have documented altered SYNGR3 expression in the context of cancer although the significance of these observations has not been further investigated." (PMID 36148399, 2022). "There are studies indicating that SYNGR3 may serve as a potential biomarker for the diagnosis and treatment of malignant tumors." (PMID 34781983, 2021). "Although the gene mutation of SYNGR3 has not been reported in human neurodegenerative diseases, post-translational modification which causes alteration in SYNGR3 protein levels has been shown to be associated with various cancers in humans." (PMID 35409005, 2022). "Currently, there is no reported association between OFCC1, Syngr3, CCDC160 and cancer." (PMID 34026368, 2021).
neurodegenerative disease (1 paper, 2022). A disorder of the central nervous system characterized by gradual and progressive loss of neural tissue and neurologic function. "Given that perturbed vesicular function is a feature of major neurodegenerative diseases, inducing SYNGR3 expression by NURR1 activators may be a potential therapeutic target to attenuate synaptic dysfunction in PD." (PMID 35409005, 2022). "As perturbed vesicular function is a feature of major neurodegenerative diseases, inducing SYNGR3 expression by NURR1 activators may be a potential therapeutic target to attenuate synaptic dysfunction in PD." (PMID 35409005, 2022).
neurological diseases (1 paper, 2022). "Several of the proteins interacting with SYNGR3 are involved in brain development and neurological diseases, for example Stiff Person Syndrome." (PMID 35409005, 2022). "The reasons why SYNGR3 expression is reduced in various human neurological disorders is yet unclear." (PMID 35409005, 2022).
tumor (1 paper, 2022). "Our immunogenomic analyses and initial identification of elevated SYNGR3 expression in HPV(+) HNSCs indicated that it is highly expressed within the Th1 subset of tumor-infiltrating T cells." (PMID 36148399, 2022). "Given this potential neuronal-independent role for SYNGR3 in immunobiology and the unique tumor-immune landscape that exists between HPV(+) and HPV(−) HNSCs, we next examined immune-related gene expression profiles." (PMID 36148399, 2022). "Regardless of the single classification method used, the combination of SYNGR3 IHC and p16 IHC was better at discriminating true tumor HPV status with SYNGR3 Antibody #1." (PMID 36148399, 2022). "To examine this more closely and characterize the number and location of SYNGR3+ cells, we performed multiplex IHC to examine SYNGR3 expression in T cells and more generally hematopoietic cells, as well as their distribution within different tumor compartments." (PMID 36148399, 2022). "Collectively, these data suggest that elevated SYNGR3 has high specificity for HPV(+) HNSC cases and further support its use as a novel tumor cell extrinsic biomarker of HPV infection." (PMID 36148399, 2022).
SYNGR3 also shares sentences with these, for which no sentence is quoted: chromophobe renal cell carcinoma (1 paper); cognitive deficits (1); Parkinson disease (1).